ZNF133 (zinc finger protein 133)
Description:
May be involved in transcriptional regulation as a repressor.
Synonyms: ZNF150; pHZ-13; pHZ-66
Tractability: PROTAC: UniProt records ubiquitination sites on it.
Gene: Protein-coding gene on chromosome 20 (18,288,265 to 18,316,996, forward strand). Ensembl gene ENSG00000125846.
Subcellular location: Nucleus
Subcellular location (Human Protein Atlas): Nucleoplasm; Vesicles
Pathways (Reactome):
Gene expression (Transcription): Generic Transcription Pathway
Gene Ontology:
Molecular function: protein binding; DNA-binding transcription factor activity; DNA-binding transcription factor activity, RNA polymerase II-specific; RNA polymerase II transcription regulatory region sequence-specific DNA binding
Biological process: negative regulation of transcription by RNA polymerase II; regulation of transcription by RNA polymerase II; negative regulation of DNA-templated transcription; regulation of DNA-templated transcription
Cellular component: nucleus
Genetic constraint (gnomAD): Loss-of-function variants: 24 observed, 55.03 expected, observed/expected ratio (o/e) 0.44, 90% interval 0.31 to 0.61. The upper end of that interval is the gene's LOEUF score, 0.61, which puts it in group 2 of 6, group 1 being the genes least tolerant of losing a copy. Missense variants: 597 observed, 806.43 expected, observed/expected ratio (o/e) 0.74, 90% interval 0.69 to 0.79. Synonymous variants: 277 observed, 315.72 expected, observed/expected ratio (o/e) 0.88, 90% interval 0.79 to 0.97.
Homologues: Orthologues: chimpanzee ZNF133 (99% identical), macaque ZNF133 (96% identical), dog ZNF133 (87% identical), rabbit ZNF133 (86% identical), pig ZNF133 (81% identical), rat Zfp133 (66% identical), guinea pig ZNF133 (65% identical), Drosophila melanogaster CG3281 (21% identical), Drosophila melanogaster CG2712 (20% identical), Drosophila melanogaster Phs (19% identical). Paralogues in human: ZNF875 (54% identical), ZNF169 (48% identical), ZNF343 (48% identical), ZNF337 (45% identical), PRDM9 (40% identical), ZNF805 (35% identical), ZNF264 (34% identical), ZNF425 (34% identical), ZFP90 (33% identical), ZNF674 (33% identical), ZNF614 (33% identical), ZNF25 (32% identical), and 50 more.
Diseases named in the same sentence as ZNF133 in open-access papers:
ZNF133 is named in the same sentence as 6 diseases in open-access papers, as found by Europe PMC text mining. Sharing a sentence is not in itself a finding about the gene and the disease. The quoted sentences say what the papers report.
osteosarcoma (2 papers, 2019 to 2020). A usually aggressive malignant bone-forming mesenchymal neoplasm, predominantly affecting adolescents and young adults. "One gene (ZNF133), which responded upon irradiation, was detected in a patient of the 2N collective and has been identified as being overexpressed in osteosarcoma." (PMID 32577795, 2020). "None of these genes has been described to promote cancer, but ZNF133 has been identified to be overexpressed in osteosarcoma." (PMID 32577795, 2020).
thyroid carcinoma (2 papers, 2020). "In TC, among those over-expressed in males, we found PPARG, previously reported in thyroid carcinomas, ERCC5, MYH11, LEMD2, ZNF133, and IDH1, the latter found to be mutated in thyroid carcinomas." (PMID 32849808, 2020). "Among the 2N patients, we detected six genes (POLR3F, SEC23B, ZNF133, C16orf45, RRN3, and NTAN1) which were overexpressed after irradiation and were duplicated in the genome of ALL patients with the second independent cancer being either meningioma or thyroid carcinoma." (PMID 32577795, 2020).
coronary atherosclerosis (1 paper, 2020). Atherosclerosis of the coronary vasculature. "According to our study, during coronary atherosclerosis, level of proteins kininogen, zinc finger protein 133, and B-cell CLL/lymphoma 6 member B protein are downregulated." (PMID 33033454, 2020).
ovarian carcinoma (1 paper, 2021). A malignant neoplasm originating from the surface ovarian epithelium. "Using 31 gene-tissue pairs in which a cancer gene is epigenetically silenced in >1% of samples, only one significant two-way interaction between promoter DNA hypermethylation and CNA loss–ZNF133 in ovarian cancer—was identified (FDR 10%)." (PMID 34862370, 2021).
cancer (3 papers, 2020 to 2021). A tumor composed of atypical neoplastic, often pleomorphic cells that invade other tissues. "High levels of ZNF133 have also been detected in irradiated fibroblasts and in childhood cancer survivors that developed second primary cancer." (PMID 33672287, 2021).
ZNF133 also shares sentences with these, for which no sentence is quoted: meningioma (1 paper).